GATA2 (GATA binding protein 2)
Diseases named in the same sentence as GATA2 in open-access papers (continued):
Sharing a sentence is not in itself a finding about the gene and the disease.
kidney cancer (3 papers, 2019 to 2022). Primary or metastatic malignant neoplasm involving the kidney. "In kidney cancer, GATA2, GATA3, GATA5 and GATA6 were mostly downregulated." (PMID 30872657, 2019). "The GATA2 is treated as a therapeutic target in NSCLC treatment development and it also related to breast and kidney cancer." (PMID 35632527, 2022).
metastatic tumors (3 papers, 2021 to 2025). "Increased GATA2/3 expression is associated with a more aggressive phenotype and associated with metastatic disease." (PMID 33579350, 2021). "GATA2 expression varied even in different metastatic tumors from the same patient collected at different anatomic locations." (PMID 40168074, 2025). "Interestingly, the average GATA2 expression in metastatic tumors was equal to the primary tumor in 8 cases (36%), less than the primary tumor in 9 cases (41%), and greater than the primary tumor in 5 cases (23%)." (PMID 40168074, 2025). "We next investigated whether GATA2 amplification correlates with PCa metastasis and thus examined the proportion of GATA2 copy number gain in PCa patients with primary and metastatic tumors in multiple independent datasets." (PMID 37550764, 2023). "Therefore, we performed GATA2 IHC on metastatic tumors collected at staging hysterectomy from 22 patients in our UW1 cohort and compared their expression to the primary tumor to determine if USC metastases have different GATA2 levels than the primary tumors." (PMID 40168074, 2025).
Parkinson disease (3 papers, 2013 to 2022). A progressive degenerative disorder of the central nervous system characterized by loss of dopamine producing neurons in the substantia nigra and the presence of Lewy bodies in the substantia nigra and locus coeruleus. "It should be noted that over-expression of SNCA and GATA2 has been implicated in Parkinson's disease and hematopoietic diseases, respectively." (PMID 36300072, 2022).
pituitary adenoma (3 papers, 2019 to 2024). "The pituitary-specific transcription factors, including PIT-1, T-PIT, SF-1, and GATA-2, involved in adenohypophysial cell differentiation and maturation are now regarded as key diagnostic tools for the further characterization of pituitary adenomas." (PMID 36060980, 2022). "In our patient’s case, the IHC staining for TSH was negative in the resected pituitary adenoma tissue, and further stains including Pit-1 and GATA-2 were not available at our center." (PMID 38311752, 2024).
squamous cell carcinoma (3 papers, 2015 to 2025). A carcinoma arising from squamous epithelial cells. "We report a case of a patient with GATA2 deficiency who developed aggressive squamous cell carcinoma (SCC) of the head and neck, an atypical manifestation of this condition." (PMID 39981594, 2025). "This case report is noteworthy for presenting an unusual occurrence of GATA2 deficiency associated with aggressive squamous cell carcinoma (SCC) in the head and neck—an atypical manifestation given the predominantly hematologic nature of the cancers related to GATA2 deficiency." (PMID 39981594, 2025).
acute erythroid leukemia (2 papers, 2020 to 2021). An acute myeloid leukemia characterized by a predominant immature erythroid population. "The co-occurrence of GATA2 and CEBPa biallelic mutations is statistically significant in bi-lineage acute erythroid leukemia (AEL)." (PMID 34359655, 2021). "Interestingly, while the majority of patients carrying GATA2 mutations were of a granulocytic (M1 or M2) subtype, mutations were also observed in acute erythroid leukemia (AEL) (AML M6 subtype)." (PMID 32330454, 2020).
adenomyosis (2 papers, 2022 to 2024). The growth of endometrial tissue inside the muscular wall of the uterine corpus. "We also did qPCR on the adenomyosis pain group and the non-pain group and discovered that several mRNAs associated with nerve growth and neuroinflammatory factors, NEFM, GATA2, HMGA1, and IGFBP6, were considerably more strongly expressed in the adenomyosis pain group than in the non-pain group." (PMID 36532077, 2022).
anaphylaxis (2 papers, 2019 to 2023). An acute hypersensitivity reaction that occurs from exposure to an allergen. "Recently, the GATA2-MITF axis has been shown to be critical for IgE/MC-mediated anaphylaxis." (PMID 36834926, 2023). "Previous studies have reported a central role for GATA-2 and MITF in CTMC differentiation and IgE-MC-mediated anaphylaxis." (PMID 31369572, 2019).
B-cell acute lymphoblastic leukemia (2 papers, 2021 to 2022). A neoplasm of lymphoblasts committed to the B-cell lineage, typically composed of small to medium-sized blast cells. "Here we identified aberrant GATA2 expression in B-cell acute lymphoblastic leukemia (B-ALL) by analyzing transcriptome sequencing data obtained from St." (PMID 35087776, 2021).
basal cell carcinoma (2 papers, 2022 to 2025). A carcinoma involving the basal cells. "Patients with a germline GATA2 mutation are known to be at increased risk for skin cancers such as basal cell carcinoma." (PMID 35328597, 2022). "A recent report described a patient with a JAK2V617F-positive PMF and an inherited GATA2 mutation who developed a basal cell carcinoma of the facial skin six years after the initial diagnosis and therapy with the JAK inhibitor ruxolitinib." (PMID 35328597, 2022).
colitis (2 papers, 2022). Inflammation of the colon. "Meanwhile, transcription factors JUN, E2F1, and GATA2 have been reported to be closely related to the occurrence and development of colitis-associated tumors." (PMID 35733095, 2022). "Additionally, previous research identified that the transcription factor GATA2 serve as an inducer for the inflammatory reaction in colitis." (PMID 35582765, 2022). "As previously reported, GATA2 can radically influence the inflammation in colitis." (PMID 35582765, 2022).
Crohn disease (2 papers, 2024 to 2025). A gastrointestinal disorder characterized by chronic inflammation involving all layers of the intestinal wall, noncaseating granulomas affecting the intestinal wall and regional lymph nodes, and transmural fibrosis. "This is a rare presentation of GATA2 deficiency manifesting initially with Crohn’s disease-like symptoms." (PMID 40821825, 2025). "One patient initially presented with Crohn’s disease, and another patient initially presented mainly with skin symptoms, revealing the phenotypic diversity of GATA2 deficiency." (PMID 40821825, 2025). "One patient presented with Crohn’s disease, a very rare manifestation of GATA2 deficiency." (PMID 40821825, 2025). "These cases expand the phenotypic spectrum of GATA2 deficiency and highlight that atypical IBD-like symptoms, including Crohn’s disease-like presentations, may cause an initial manifestation." (PMID 40821825, 2025).
Down syndrome (2 papers, 2020 to 2025). "GATA-2 mutation was detected in Kasumi-4, derived from childhood CML in a patient without Down syndrome." (PMID 32180206, 2020).
encephalitis (2 papers, 2022 to 2025). An acute inflammatory process affecting the brain parenchyma. "The finding of AAN-I-IFN in patients with WNV encephalitis or TBE, in turn, also suggests that the extremely rare cases of WNV encephalitis or TBE in patients with deleterious mutations of GATA2 or IRF7 are probably also due to impaired type I IFN antiviral immunity." (PMID 41608126, 2025).
glioblastoma (2 papers, 2024 to 2025). The most malignant astrocytic tumor (WHO grade IV). "The gene MECOM, associated with poor prognosis in glioblastoma, has been demonstrated to interact with GATA2 and other transcription factors." (PMID 41154393, 2025).
gonadotroph adenoma (2 papers, 2020 to 2021). "Further investigation with IHC for GATA2, GATA3 and alpha subunit would help the differentiation between true null cell adenomas and gonadotroph adenomas and thus provide the true prevalence of null cell adenomas." (PMID 34589436, 2021). "Intriguingly, we revealed distinct groups as follows: 1) somatotroph adenoma: high POU1F1 and high DLK1; 2) lactotroph adenoma: high POU1F1 and low DLK1; 3) gonadotroph adenoma: high FSHB and low DLK1, followed by high GATA2 and low DLK1; and 4) corticotroph adenoma: high TBX19 and low DLK1." (PMID 33472171, 2020).
heart failure (2 papers, 2022 to 2025). Inability of the heart to pump blood at an adequate rate to meet tissue metabolic requirements. "Because heart failure is associated with a strong increase in mechanical overload, we hypothesized that this might be a crucial trigger for GATA2 dysregulation in this situation." (PMID 36552246, 2022). "Instead, endothelial loss of GATA2 led to a strong upregulation of two related long non-coding RNAs in these cells, which are taken up by cardiac myocytes where they alter stress-dependent signal transduction and ultimately induce heart failure." (PMID 36552246, 2022). "Endothelial GATA2 knock-out (G2-EC-KO) mice develop heart failure and defective myocardial signal transduction during pressure overload, indicating that the GATA2 downregulation is maladaptive." (PMID 36552246, 2022). "GATA2 became downregulated by mechanical overload in endothelial cells, and this promoted the development of heart failure, indicating that GATA2 is protective and prevents the expression of a maladaptive endothelial gene program." (PMID 36552246, 2022). "Decreased abundance of GATA2 in human failing hearts indicates that our findings might be relevant for patients with heart failure." (PMID 36552246, 2022). "Next, we wanted to assess how reduced GATA2 levels in endothelial cells might lead to cardiac failure." (PMID 36552246, 2022). "We demonstrate in this study that inducible genetic deletion of GATA2 in endothelial cells of adult mice precipitated cardiac failure during experimental pressure overload without impairment of myocardial capillarization." (PMID 36552246, 2022). "GATA2 knockout causes endothelial cells to release two long noncoding RNAs (AK037972 and AK038629), which may trigger heart failure by affecting the stress reactivity of cardiomyocytes." (PMID 39823264, 2025).
herpes zoster (2 papers, 2022 to 2024). A common dermal and neurologic disorder caused by reactivation of the varicella-zoster virus that has remained dormant within dorsal root ganglia, often for decades, after the patient's initial exposure to the virus in the form of varicella (chickenpox). "Studies have indicated that patients with significant GATA2 gene deletions may exhibit typical infectious manifestations of NK cell deficiency, including widespread infections with VZV and severe herpes zoster." (PMID 39253091, 2024).
Hydroureter (2 papers, 2021 to 2025). The distention of the ureter with urine. "In another study, conditional deletion of Gata2 in the mesenchyme using Tbx18-Cre resulted in hydroureter formation at birth." (PMID 40196482, 2025). "Recently, it was reported that ureteric mesenchyme-specific conditional GATA2 deletion mice also phenocopied similar hydroureter anomalies." (PMID 33803938, 2021). "However, the YAC-rescued compound Gata2 mutant neonates failed to develop a proper ureter–bladder connection and consequently succumbed to urinary tract anomalies such as hydronephrosis and megaureter." (PMID 33803938, 2021).
Hyperglycemia (2 papers, 2019 to 2023). An increased concentration of glucose in the blood. "GATA2 mRNA levels in hyperglycemia-induced HUVEC were significantly lower than HUVEC treated with normal glucose concentrations (positive control) at 6, 12, and 24 hours (p=0.03 in all times)." (PMID 37042872, 2023). "Hyperglycemia increased Bmi1 and GATA2 level, and decrease MICA/B and p-AMPK in vivo, as determined with IHC assessment." (PMID 31088566, 2019).
infectious mononucleosis (2 papers, 2017 to 2021). A condition characterized by an increase in mononuclear white blood cells and swollen lymph nodes, which is usually caused by infection with the Epstein-Barr virus. "A third patient with a missense mutation (R396Q) in one allele of GATA2 presented with EBV infectious mononucleosis and was hospitalized twice, once for severe fatigue with headache and rash, and a second time for dehydration and malaise with 44,000 copies of EBV DNA/ml of blood." (PMID 29375553, 2017).
inflammatory bowel disease (2 papers, 2022 to 2025). A spectrum of small and large bowel inflammatory diseases of unknown etiology. "Although GATA2 deficiency has been linked to systemic inflammation, gastrointestinal involvement mimicking inflammatory bowel disease (IBD) is extremely rare." (PMID 40821825, 2025).
latent infection (2 papers, 2015 to 2019). "Taken together, these studies showed that latency-associated changes in hsa-miR-92a result in increased GATA2, which drives the expression of cIL-10 during latent infection." (PMID 25772624, 2015). "Taken together, then it appears that expression of LAcmvIL-10 during latent infection results in downregulation of cellular hsa-miR-92a, which in turn leads to the upregulation of the myeloid transcription factor GATA2." (PMID 25772624, 2015).
Li-Fraumeni syndrome (2 papers, 2019 to 2021).
liver cancer (2 papers, 2017 to 2022). An epithelial or non-epithelial malignant neoplasm that arises from the liver. "Furthermore, attenuated expression of GATA2 promotes migration and invasion of HCC cells in vitro and be associated with poor prognosis of liver cancer." (PMID 29156748, 2017).
lymph node metastases (2 papers, 2021 to 2023). "KIRC's pathological grades, clinical stages, and lymph node metastases were closely related to GATA2 and GATA5 levels." (PMID 36961416, 2023).
malaria (2 papers, 2017 to 2022). Malaria is a serious and sometimes fatal disease caused by a parasite that commonly infects a certain type of mosquito which feeds on humans. "Future studies should examine the factors that influence the function of GATA1/GATA2 during malaria since it is clear that a variety of intermediate molecules besides those described here could also affect each protein’s function." (PMID 28938907, 2017). "Infection with malaria induced an almost linear increase in Gata2 expression in unvaccinated mice, which did not significantly differ from that in vaccinated mice." (PMID 35214745, 2022). "In this study, it was shown that GATA1 and GATA2, two master regulators of erythropoiesis, may not function appropriately during acute malaria." (PMID 28938907, 2017).
Mycobacterium avium infection (2 papers, 2012 to 2024). "Three patients with HLH, one with Mycobacterium avium infection, one with Epstein–Barr virus (EBV) infection, and one with Mycobacterium kansasii infection, were all subsequently found to have a defect in the GATA2 gene through genetic testing." (PMID 38730328, 2024).
myelofibrosis (2 papers, 2018 to 2022). A partial or complete replacement of the bone marrow stroma by fibrous tissue. "Given the important role of GATA transcriptional regulators in myelofibrosis pathogenesis and in Tet2-mutant AML, we performed quantitative PCR for Gata1 and Gata2 in donor-derived MEPs isolated from vehicle- and inhibitor-treated mice." (PMID 29355841, 2018).
pneumonia (2 papers, 2023 to 2026). An acute, acute and chronic, or chronic inflammation focally or diffusely affecting the lung parenchyma, caused by an infection in one or both of the lungs (by bacteria, viruses, fungi, or mycoplasma.). "A somatic GATA2 pathogenic, frameshift variant (p.Ser340AsnfsTer39, variant allele frequency 11.6%) was detected from a young female adult patient (Case 9) with a history of recurrent infection (tuberculosis, pneumonia, EBV, CMV, and BKV)." (PMID 37325673, 2023).
rheumatism (2 papers, 2022 to 2025). "In non-GATA2 mutated MDS rheumatologic disorders usually develop months/years after MDS diagnosis, whereas in GATA2 deficiency they can develop independently from hematological manifestations even without any other clinical symptom." (PMID 35769478, 2022).
schizophrenia (2 papers, 2020 to 2025). A major psychotic disorder characterized by abnormalities in the perception or expression of reality. "Based on family history, it is likely that her mother had GATA2 deficiency, and she may have been genetically predisposed to schizophrenia from her father rather than her mother." (PMID 40264496, 2025). "In another postmortem study of the DLPFC in schizophrenia, miR-132 was observed to be dysregulated and this was supported by the altered expression of its target genes, including DNMT3A, GATA2, and DPYSL3, which are known to be related to the development of the nervous system and schizophrenia." (PMID 32764320, 2020).
Sepsis (2 papers, 2022). Sepsis is defined as life-threatening organ dysfunction caused by a dysregulated host response to infection. "In the two groups of different expression trend modules, the core genes such as CD160, GATA2, GNLY, IL2RB and TGFBR3 were downregulated in the sepsis group, while genes such as ELANE, IL1R1, TLR5, FCGR1A, MAPK14 and PCSK9 were upregulated." (PMID 35332254, 2022).
skin cancer (2 papers, 2024 to 2025). "There are even several reports of skin cancers developed in GATA2–deficiency patients; basal cell carcinoma, squamous cell carcinoma, and malignant melanoma." (PMID 39614632, 2024).
Thrombocytopenia (2 papers, 2023 to 2025). A reduction in the number of circulating thrombocytes. "She had been noted to have a longstanding history of thrombocytopenia, which is atypical for GATA2 deficiency." (PMID 40148527, 2025). "Consequently, the RUNX1 deletion was missed, and her life-long thrombocytopenia and AML were inappropriately attributed to the germline GATA2 variants." (PMID 40148527, 2025).
tuberculosis (2 papers, 2023 to 2024). A chronic, recurrent infection caused by the bacterium Mycobacterium tuberculosis.
type 1 diabetes (2 papers, 2014 to 2024). "The trans-eSNPs showing mediation by GATA2 (3q21.3), FCN1 (9q34.3), and RPS26 (12q13.2) are also associated with white blood cell subtypes, systemic inflammation (and FCN1 protein activity), and type 1 diabetes risk, respectively." (PMID 25474530, 2014).
vasculitis (2 papers, 2022). "Multiple small vessel aneurysms found in Patient 10 may be secondary to vasculitis, or could also represent a novel vascular feature associated with GATA2 deficiency." (PMID 34893945, 2022). "Moreover, the most prevalent rheumatologic manifestations in the non-GATA2 mutated MDS group are vasculitis, namely polyarteritis nodosa and giant-cell arteritis, differently from GATA2 mutated patients." (PMID 35769478, 2022).
acute kidney injury (1 paper, 2025). Sudden and sustained deterioration of the kidney function characterized by decreased glomerular filtration rate, increased serum creatinine or oliguria. "The IL-6/GATA2/SERPINE1 pathway mediates cellular senescence after acute kidney injury, and inhibiting IL-6 can alleviate AKI-induced cellular senescence, providing an important basis for exploring new therapeutic strategies." (PMID 40007559, 2025). "In summary, this study not only unveils a novel mechanism of IL-6/GATA2/SERPINE1-mediated cell senescence in acute kidney injury but also provides preliminary evidence for TCZ as an effective treatment for AKI-induced cell senescence." (PMID 40007559, 2025).